FGF23 (fibroblast growth factor 23)
Diseases named in the same sentence as FGF23 in open-access papers (continued):
Sharing a sentence is not in itself a finding about the gene and the disease.
rickets (continued). "Although adult HF patients also have lower serum Ca than healthy elderly adults, the disease seems to differ from HF in infants with rickets since, in contrast to nutritional rickets in children, serum Pi is slightly and FGF23 markedly elevated in adult HF." (PMID 40565034, 2025). "Mutations in genes responsible for vitamin D metabolism or function, the production or breakdown of fibroblast growth factor 23, renal phosphate regulation, or bone mineralization can lead to the hereditary form of rickets." (PMID 38706696, 2024). "FGF23 is particularly relevant in the context of metabolic bone diseases, such as osteoporosis and rickets, because dysregulation of FGF23 levels can disrupt mineral metabolism and bone health." (PMID 38951759, 2024). "The original reports of ARHR2 by Levy-Litan and colleagues described three patients with rickets, two of whom had FGF23 levels at the upper limit of normal—50 pg/mL and 47 pg/mL (reference range of 10–50 pg/mL)." (PMID 37871131, 2024). "The measurement of FGF23 levels is most useful in the diagnostic workup of untreated patients with phosphopenic rickets to differentiate between FGF23-mediated and other forms of rickets." (PMID 37047636, 2023). "In conclusion, this review summarizes significant available information on vitamin D and FGF23 metabolism in the pediatric population, in normal conditions as well as in several diseases such as rickets, CKD and hypophosphatemic disorders." (PMID 37047636, 2023). "FGF23 is of great importance, both for the differential diagnosis of the various forms of rickets, and for the subsequent monitoring of the effectiveness of drug treatment." (PMID 36440231, 2022). "Among skeletal symptoms persistent to FGF23 blocking treatment, linear growth impairment has shown to be improved only to a very limited extent by Burosumab treatment despite resolution of rickets." (PMID 35399930, 2022). "The DMP1-null mice exhibited poor skeletal mineralization and rickets combined with low serum phosphate and elevated serum fibroblastic growth factor 23 (FGF23)." (PMID 35558889, 2022). "Both mouse lines exhibited hypophosphatemic rickets along with elevated FGF23 levels in serum and bone." (PMID 36246908, 2022). "A strong inverse correlation between FGF23 and hemoglobin has been suggested to link low iron status in the etiology of rickets in Gambian children." (PMID 35405984, 2022). "FGF23-inhibiting antibody treatment can normalize serum phosphate levels and to improve rickets in XLH patients." (PMID 35399930, 2022). "Mean FGF23 levels were significantly higher in TIO patients compared to those with FGF23-mediated rickets due to genetic defects, but varied widely in both groups." (PMID 34910242, 2022). "With availability of Fibroblast-like Growth Factor 23 (FGF23) inhibiting therapies, normalization of phosphate levels can be achieved in most patients with profound improvement of rickets." (PMID 35399930, 2022). "Diagnosis of FGF23-mediated phosphopenic rickets, including XLH, should always be questioned in a treatment-naïve patient showing nephrocalcinosis." (PMID 34910242, 2022). "Oral Pi supplementation is usually indicated for FGF23-independent phosphopenic rickets, whereas the conventional treatment of FGF23-dependent types of rickets includes a combination of Pi and activated vitamin D." (PMID 34199067, 2021). "Hypophosphatemic rickets is a heterogeneous group of entities due to renal Pi wasting wherein fibroblast growth factor 23 (FGF23) often plays a major role." (PMID 34199067, 2021). "Hypophosphatemic rickets in several sclerosing bone, skin or soft tissue disorders is believed to result from increased secretion of FGF23 or related phosphaturic hormones by the aberrant cells." (PMID 33815294, 2021).
rickets (continued). "Treatment options for XLH are currently expanding beyond phosphate and vitamin D. A novel treatment with burosumab, a FGF-23 antibody, has shown superiority to conventional treatments regarding improvement of rickets and linear growth." (PMID 32582030, 2020). "In people with CKD, hypovitaminosis D and increased serum PTH and FGF‐23 concentrations are associated with disease progression and decreased survival." (PMID 33128421, 2020). "Nevertheless, it needs to be tested if anti-FGF23 antibody can improve or cure rickets/osteomalacia or their clinical presentations such as bone pain and muscle weakness." (PMID 30820831, 2019). "Cases of rickets have, however, been reported and have been attributed predominantly to a chronically low dietary calcium (Ca) intake leading to a 1,25(OH)2D-driven increase in FGF23 leading to urinary phosphate (P) wasting and rickets." (PMID 23246670, 2013). "Grossly elevated FGF23 concentrations have been detected in a large percentage of Gambian children with rickets-like bone deformities using the C-terminal ELISA." (PMID 22648001, 2013). "We have previously reported the presence of elevated FGF23 concentrations in Gambian children with a history of rickets-like bone deformities as determined by the C-terminal Immutopics ELISA assay." (PMID 22648001, 2013). "The original clinical case series of Gambian children with bone deformities consistent with rickets indicated that 70% of the patients had elevated FGF23 concentrations." (PMID 22023931, 2012). "One study in Gambian children with rickets found extremely high FGF-23 in these patients along with high 1,25(OH)2D and low dietary calcium." (PMID 22984574, 2012). "Iron deficiency anaemia is prevalent in The Gambia and concentrations of fibroblast growth factor-23 FGF23 are elevated in a large percentage of Gambian children with rickets-like bone deformity." (PMID 22465847, 2012). "A clinical case-series of 46 children with bone deformities consistent with rickets, conducted in The Gambia, indicated abnormally elevated concentrations of plasma fibroblast growth factor-23 (FGF23) in the majority of cases." (PMID 22023931, 2012). "In conclusion, there is a stronger relationship between FGF23 and haemoglobin in Gambian children with a history of rickets compared to local community children." (PMID 22465847, 2012). "Hypophosphatemic rickets can be divided into FGF23-mediated and non-FGF23-mediated forms." (PMID 41445557, 2025). "Moreover, FGF23 levels were found to be low (7.9 ng/L, nv), indicating FGF23-independent mechanisms beyond rickets." (PMID 40225330, 2025). "Osteocyte-specific deletion of Fgf23 in Dmp1KO mice also resulted in a partial rescue of most trabecular and cortical bone defects, with the exception of cortical bone expansion, consistent with residual features of rickets." (PMID 37943605, 2023). "Furthermore, newly developed therapeutic strategies targeting FGF23 have shown promising short-term results in normalizing growth and decreasing the severity of rickets." (PMID 35055123, 2022). "The levels of the renal metabolite may be decreased in FGF-23-dependent rickets or increased in FGF-23-independent rickets." (PMID 35956239, 2022). "It is also possible that the low iFGF23 in many of the rickets children may have been due to their low plasma calcium, because calcium is known to be a modulator of circulating FGF23." (PMID 32276153, 2020). "This may be explained by a chronically low dietary Ca intake and increased 1,25(OH)2D-driven increase in FGF23 as described in the majority of Gambian nutritional rickets." (PMID 23246670, 2013). "Elevated serum levels of FGF23 have been demonstrated in children with rickets and diminished bone mineral density, but also a direct FGF23 effect has been hypothesized on the heart." (PMID 24168888, 2013).
rickets (continued). "The cKO mice did not mimic the human skeleton abnormalities of osteosclerotic bone dysplasia, but exhibited rickets (softer bone) along with a significant reduction of serum phosphate level and a remarkable elevation of serum FGF23, a hormone known to promote phosphate wasting." (PMID 22615579, 2012). "This study provided evidence in support of the calcium deficiency hypothesis leading to urinary phosphate wasting and rickets and identified glomerular filtration rate and iron status as possible modulators of FGF23 metabolic pathways." (PMID 22023931, 2012). "It is possible that poor iron status may also play a role in the elevation of FGF23 concentrations and therefore may be a contributing factor to Gambian rickets." (PMID 22465847, 2012). "One of the interesting findings from this study was that FGF23 was not only elevated in children with a personal or family history of rickets-like bone deformities but also, albeit to a lesser extent, in some apparently healthy children living in the local community." (PMID 22465847, 2012). "This retrospective analysis assessed whether treatment with burosumab, a fully human IgG1 monoclonal antibody to fibroblast growth factor 23 approved for treatment of rickets in XLH, improves lower limb malalignment toward age-specific normal values in children with XLH." (PMID 40433251, 2024). "The most common types of phosphopenic rickets are the Fibroblast Growth Factor 23 (FGF23) mediated disorders, including XLH rickets, autosomal dominant and autosomal recessive forms of hypophosphatemic rickets (less common) and tumor induced osteomalacia, which may be also present in childhood." (PMID 36817604, 2023). "X-linked hypophosphatemia (XLH) is the most common form of inherited rickets caused by a mutation in the phosphate regulating gene with homology to endopeptidase located on the X chromosome (PHEX), which leads to elevated serum levels of fibroblast growth factor 23 (FGF23)." (PMID 34043707, 2021). "Vitamin D deficiency or hereditary factors resulting in changes of 1,25(OH)2D, PTH, and FGF23 levels could cause genetic or non-hereditary rickets." (PMID 33015068, 2020). "Therefore, we performed mutational screening of the PHEX promoter region and other genes responsible for FGF23-related rickets; this analysis identified no mutations, so we concluded that the p.Gly316Val mutation is likely to be causative of XLH." (PMID 25861491, 2015). "Western blotting has provided evidence that elevated FGF23 concentrations, as determined by the C-terminal Immutopics ELISA, measured in Gambian children with and without rickets-like bone deformities was not caused by an increased proportion of circulating inactive C-terminal fragments." (PMID 22648001, 2013). "To investigate the relationship between circulating FGF23 and haemoglobin concentrations we used an age-adjusted linear regression model on data from children < 18 y of age with a family or personal history of rickets-like bone deformity (BD) (n = 108) and from the local community (LC) (n = 382)." (PMID 22465847, 2012). "Data show that levels of intact FGF23 (iFGF23) increase more with an FCM infusion compared to other IV irons, potentially leading to a cascade of metabolic events including high FGF23, HPP, hypovitaminosis D, hypocalcemia, and secondary hyperparathyroidism." (PMID 39935027, 2025). "FGF-23 concentrations were found to be within the normal range, thus ruling out FGF23-dependent forms of rickets." (PMID 40225330, 2025). "Tumor-induced osteomalacia (TIO), or oncogenic osteomalacia, results from excessive fibroblast growth factor 23 (FGF23) secretion by phosphaturic mesenchymal tumors (PMTs), leading to renal phosphate wasting and hypovitaminosis D." (PMID 40867266, 2025). "Burosumab is a recent treatment for XLH that targets excess circulating fibroblast growth factor 23 (FGF23), and its benefits on rickets have been demonstrated." (PMID 36398111, 2022).
rickets (continued). "All but one had elevated alkaline phosphatase (ALP) levels, a marker for active rickets, whereas some also had elevated PTH and FGF23 levels." (PMID 33869987, 2021). "As a result of the increased FGF23 concentrations patients with XLH, ADHR, ARHR type 1 and 2 present with rickets, hypophosphatemia, phosphaturia and inappropriately normal serum 1,25-dihydroxyvitamin D3 concentrations." (PMID 21747952, 2011). "Burosumab, a fully humanized immunoglobin G1 monoclonal antibody to FGF23, is predominantly used in the management of paediatric and adult patients with XLH and ameliorates many of the clinical features, including hypophosphataemia and rickets." (PMID 41445557, 2025). "A raised FGF23 is not a distinguishing feature of this syndrome, however we found elevated FGF23 at first presentation with rickets in 2 out of 3 cases." (PMID 23246670, 2013). "In conclusion, a difference in proportion of cleaved FGF23 hormone does not explain the presence of high FGF23 in Gambian children with rickets-like bone deformities and in children from the local community." (PMID 22648001, 2013). "Fibroblast growth factor 23 (FGF23) is grossly elevated in Gambian children with rickets and, at a lower prevalence, in those without bone deformities." (PMID 22648001, 2013). "The aim of this study was to determine if there was a relationship between haemoglobin, as a marker of iron status, and FGF23 in samples from children with and without a history of rickets-like bone deformities in The Gambia." (PMID 22465847, 2012). "This is not surprising because PHEX or FGF23 related rickets have a distinctive inheritance mode that differs from the autosomal recessive inheritance of the rickets studied here." (PMID 21747952, 2011). "In addition, burosumab, a humanized FGF23 antibody, has only been approved in patients with XLH and TIO, but not in other forms of FGF23-driven phosphopenic rickets." (PMID 34910242, 2022). "As the degree of elevated FGF23 does not allow for discrimination between the various forms of FGF23-mediated rickets, final diagnosis may require additional genetic testing, especially in cases of negative family history." (PMID 34910242, 2022). "In summary, this study demonstrated that elevated plasma C-FGF23 concentrations normalised over time in Gambian children with a history of rickets but not in apparently healthy local children, suggesting that the aetiology of a raised FGF23 concentration is different in these two groups." (PMID 24258305, 2014). "Surprisingly, both the global and mineralized tissue-specific cKO mice developed hypophosphatemic rickets (but not osteosclerosis), along with a significant downregulation of osteoblast differentiation markers and a dramatic elevation of fibroblast growth factor 23 (FGF23) in the serum and bone." (PMID 22615579, 2012). "The aim of the study was to determine whether C-terminal FGF23 fragments were present in Gambian plasma samples and therefore detected using the Immutopics ELISA and if this was different in plasma from children with and without rickets-like bone deformities." (PMID 22648001, 2013). "Sanger sequencing and multiplex ligand-dependent probe amplification analysis of PHEX and Sanger sequencing of FGF23, DMP1, ENPP1KL, and FAM20C were performed to assess genotype in patients with HH with or without rickets in all pediatric hospital departments across Norway." (PMID 26543054, 2016).
cardiac hypertrophy (139 papers, 2013 to 2025). "After correction for age, sex and interim valvular interventions, FGF23 was the only biomarker next to NT-proBNP significantly associated with pressure overload, consistent with its role in ventricular hypertrophy and myocardial damage." (PMID 40823165, 2025). "Fibroblast growth factor 23 (FGF-23) is a phosphaturic hormone elevated in patients with renal insufficiency and associated with cardiac hypertrophy and pathological cardiac remodeling." (PMID 41226753, 2025). "High levels of FGF23 lead to lower levels of active vitamin D, which activate the renin‐angiotensin‐aldosterone system causing cardiac hypertrophy and fibrosis." (PMID 38124483, 2024). "Iron deficiency, as with chronic inflammation, is associated with cardiac hypertrophy and myocardial fibrosis due to the accumulation of increased production and decreased degradation of FGF-23." (PMID 38941000, 2024). "Experimental activation of the FGF23/FGFR pathway has been implicated in cardiac hypertrophy and fibrosis, supporting its role as a potential therapeutic target." (PMID 38420755, 2024). "To determine the potential role of FGF23/FGFR4 in pregnancy-associated cardiac hypertrophy, we conducted histological analyses of hearts from wild-type and FGFR4−/− mice." (PMID 39452290, 2024). "To interpret the paradoxical phenomena, we surmised that there were many factors leading to cardiac hypertrophy in uremic patients, while elevated FGF23 was only one of the complex risk factors." (PMID 35801203, 2022). "Elevated FGF23 levels are associated with many cardiovascular conditions, including cardiac hypertrophy, atherosclerosis, vascular calcification, and endothelial dysfunction." (PMID 36102251, 2022). "Exposure of primary mouse cardiomyocytes to FGF-23 led to an elevated intracellular Ca2+ level, which has been linked to a high risk of cardiac hypertrophy." (PMID 35008591, 2021). "Elevated FGF23 has emerged as having a strong association with cardiovascular events, cardiac hypertrophy, congestive heart failure, and volume overload." (PMID 34765890, 2021). "It has been shown that increased FGF-23 levels induce cardiac hypertrophy and dysfunction and are associated with increased cardiovascular mortality in renal patients." (PMID 34867481, 2021). "In in vitro and in vivo studies, FGF23 has been directly implicated in the development of cardiac hypertrophy and fibrosis." (PMID 33534825, 2021). "Recent research provides evidence that a high plasma level of fibroblast growth factor-23 (FGF)-23 is a hallmark of cardiac damage resulting in deleterious remodelling and the induction of cardiac hypertrophy." (PMID 33767635, 2021). "By performing a graded ureter obstruction model in combination with a systemic expression of humanized S100A8, S100A12, and S100A9 in C57BL/6 mice, the association between S100/RAGE/FGF23 and cardiac hypertrophy was revealed." (PMID 32150864, 2020). "Fibroblast growth factor 23 (FGF23) is a circulating hormone that is associated with cardiac hypertrophy and also acutely elevates intracellular Ca2+ and increases cardiac contractility." (PMID 32903789, 2020). "Experimental and clinical evidences point out a role of FGF-23 in CKD-associated cardiac hypertrophy since FGF-23 increases in patients with CKD and its concentration is correlated to cardiac hypertrophy." (PMID 33777999, 2020). "As FGF-23 promotes myocardial remodelling and cardiac hypertrophy, it can cause or enhance hypertrophy-related ectopic activity and automaticity, leading to AF." (PMID 30615112, 2019). "The association between FGF23 and cardiac remodeling in klotho-deficient animals suggests that FGF23 affects cardiac hypertrophy and fibrosis only in states of high phosphate and klotho deficiency." (PMID 29977226, 2018). "Both clinical and experimental studies have causally linked FGF23 to cardiac hypertrophy, cardiac dysfunction and congestive heart failure." (PMID 28795324, 2018).